HIF1A (hypoxia inducible factor 1 subunit alpha)
Diseases named in the same sentence as HIF1A in open-access papers (continued):
Sharing a sentence is not in itself a finding about the gene and the disease.
tumor (continued). "In tumor cells, HIF-1α was located in cell nuclei, while POH was predominantly located in the cytoplasm, consistent with the fact that POH lacks the C-terminal nuclear localization signal of HIFα, which is important for HIF nuclear translocation." (PMID 21203417, 2010). "The expression of STAT3C, which mimics the constitutive STAT3 activation observed in many tumours, is thus sufficient to promote aerobic glycolysis, acting at least in part through transcriptional induction of Hif-1α." (PMID 21084727, 2010). "Nine out of 28 tumours (32%) showed perinecrotic HIF-1α expression in grade 1 tumours compared with 70% grade 2 and grade 3 tumours (χ2-test, p = 0.004)." (PMID 20565904, 2010). "Extensive overexpression was linked with HIF1α and LDH5 upregulation, indicating hypoxic tumours and an acidic intra-tumoral environment." (PMID 20842118, 2010). "Based on this, targeting tumoral HIF-1α is under intense investigation as a therapeutic strategy to inhibit angiogenesis and tumor growth." (PMID 20398289, 2010). "In order to evaluate the hypoxia status of FGF8b and mock tumours further, we immunostained tumours against HIF1α, which mediates acute molecular responses to hypoxia." (PMID 21034500, 2010). "In clinical samples, HIF-1α is found elevated and correlates with tumor progression, aggressive behavior, and patient prognosis in several types of carcinoma including those of the ovary, breast, prostate, lung, renal, glial, and melanoma." (PMID 20953377, 2010). "HIF1α levels were significantly up-regulated in and around tumour tissue at 20W (p < 0,001), 25W (in: p < 0,001; around: p < 0,05) and 30W DEN (p < 0,001) compared to adjacant non-HCC tissue." (PMID 20727157, 2010). "Early work on HIFs and cancer focused on HIF1α and demonstrated that the majority of tumour cells responded to hypoxia by stabilizing the HIF1α protein." (PMID 20104230, 2010). "Positive expression of both CAIX and Glut-1 was seen in 68% of the perinecrotic HIF-1α expressing tumours compared to 32% of the diffuse group (χ2-test, 0.007)." (PMID 20565904, 2010). "Immunostaining of tumor sections for HIF-1α expression confirmed that the tumors resulting from the injection of shHIF cells had decreased HIF-1α expression compared with control tumors resulting from the injection of cells infected with the empty vector." (PMID 20515450, 2010). "More activation of HIF-1α and its target genes would give more tumour cells a survival advantage in a hypoxic environment." (PMID 20565904, 2010). "This study was confirmed by performing immunofluorescence of HIF-1α and p-eIF2α proteins in tumor sections of both groups of animals." (PMID 21085474, 2010). "Hypoxic conditions also increase the activity of hypoxia-inducible factor (HIF-1α) and VEGF, which are strongly associated with both tumour angiogenesis and EOC tumour aggressiveness." (PMID 20182531, 2010). "The specificity of zinc action of HIF-1α was confirmed by Western immunoblotting of tumor tissue extracts." (PMID 21179202, 2010). "Correlation of HIF-1α with tumour stage, tumour grade, or myometrial invasion is still under discussion." (PMID 20169098, 2010). "The overexpression of HIF1A factor is related to local invasion and metastatic spread of tumor cells." (PMID 20175888, 2010). "These paradoxical observations seem to suggest that the roles of HIF-1α in tumor development and/or in cancer therapy are conditional and that the conditions remain to be further clarified so that this important tumor-related factor can be better employed." (PMID 20932347, 2010). "This study is the first to demonstrate that TPZ, a hypoxia-selective cytotoxin, induces an unexpected downregulation of hypoxia-dependent and mitogen-dependent HIF-1α accumulation in human tumor cell lines originating from various tissues." (PMID 21085474, 2010).
tumor (continued). "Genes promoting cancer progression (u-PAR, VEGFC, and HIF1α) and tumour suppression (VHL, RASSF1, and FHIT) of NSCLC were significantly (P<0.05) down- or upregulated after Enz treatment in H460, A549, and H1299 cells, respectively." (PMID 20736951, 2010). "Magnon's findings supported a crucial role for angiogenesis inhibitors in shifting the fate of radiation-induced HIF-1α activity from hypoxia-induced tumor radioresistance to hypoxia-induced tumor apoptosis." (PMID 21143841, 2010). "The CAIX plasma level was compared with HIF-1α expression and the Ki-67 tumour tissues index using the Spearman's Rank test." (PMID 20461082, 2010). "Many studies also report higher expression of proangiogenic factors such as VEGF-A, hepatic growth factor (HGF), HIF-1α, and inducible nitric oxide in the surrounding liver than in the tumor tissues." (PMID 20716344, 2010). "Tumor hypoxia is marked by enhanced expression of hypoxia-inducible factor-α (HIF-1α) and glucose transporter-1 (Glut-1)." (PMID 20569445, 2010). "But when these manipulated 786-0 cells were grown in vivo as xenografts, a different tumor growth profile emerged showing that HIF-2α caused significantly increased growth rates and HIF-1α caused significantly decreased growth rates when compared to EV tumors." (PMID 20652061, 2010). "In GBMs, HIF-1α is primarily localized in pseudopalisading cells around areas of necrosis and in tumor cells infiltrating the brain at the tumor margin." (PMID 20414333, 2010). "Several isoforms of HIF-1α resulting from alternative splicing have been described in various human tumour cell lines or tissues." (PMID 20624301, 2010). "In tumor cells, HIF-1α can also be regulated by other genetic factors, such as oncogenes (Ras and phosphoinositide 3-kinase) or loss of tumor suppressors (VHL or PTEN) even under aerobic conditions." (PMID 21179202, 2010). "It is not yet clear if genomic instability can arise through prolonged HIF-1α stabilization under aerobic conditions as would occur during tumor initiation and progression." (PMID 20181022, 2010). "In human tumours, HIF-1α protein is overexpressed because of intratumoural hypoxia and genetic alterations affecting key oncogenes and tumour suppressor genes." (PMID 20624301, 2010). "As for CAIX expression, the same immmunostaining intensity pattern was observed for HIF-1α and Ki-67 expression, which showed a nuclear staining, where 133 of 555 (24%) tumours showed high HIF-1α immunoreactivity." (PMID 20461082, 2010). "Randall Johnson and colleagues reported in a mouse model that the endothelial cell-selective knockdown of HIF-1α markedly impairs tumor angiogenesis." (PMID 19482033, 2010). "HIF-1α is centrally involved in multiple aspects of tumorigenesis including tumor cell proliferation, angiogenesis, metastasis, as well as the response to chemo- and radiotherapy." (PMID 20706634, 2010). "Mutated VHL prevents appropriate normoxic degradation of HIF-1α and, as such, CAIX is highly expressed in mutated VHL-related tumours, independently of the extent of tumour necrosis." (PMID 20461082, 2010). "HIF-1α is often upregulated in tumors leading to more aggressive tumor growth and chemoresistance, therefore representing an important target for antitumor intervention." (PMID 21179202, 2010). "Through modulation of the expression of at least 70 genes, HIF-1α is extensively involved in tumor survival, aggressive progression, drug resistance and angiogenesis." (PMID 20932347, 2010). "Significant statistical association was found between tumour grade and HIF-1αTAG (P = 0.048), and total HIF-1α (P = 0.048) mRNA levels." (PMID 20624301, 2010).
tumor (continued). "In our study, this was supported by the positive correlation between immunostaining for CAIX and HIF-1α expression in tumour tissue (P=0.036)." (PMID 20461082, 2010). "Our results suggest that Enz has a major role in downregulating the u-PAR through Sp1/Sp3 and c-Jun(AP-1), besides HIF1α and VEGFC that are implicated in tumour growth and metastasis, in parallel to upregulating tumour-suppressors relevant for NSCLC." (PMID 20736951, 2010). "In 56% of the tumours (30/54) with perinecrotic HIF-1α expression, we observed central/perinecrotic p27kip1 staining (McNemar; p < 0.0001)." (PMID 20565904, 2010). "Intracellular HIF1α concentrations are tightly regulated by the von Hippel–Lindau tumour-suppressor protein, a product of the third tumour-suppressor gene upregulated by Enz in our study, and a component of the E3 ubiquitin ligase system." (PMID 20736951, 2010). "These cells along with malignant cells are able to secrete pro-angiogenic factors including vascular endothelial growth factor (VEGF) mediated by the hypoxia induced transcription factor-1 (HIF-1α), which induce tumor blood vessel formation." (PMID 21151768, 2010). "Herein, we found that pre-treatment of OVCAR-3 tumor cells with ABZ inhibits hypoxia or DFO-induced HIF-1α accumulation." (PMID 20398289, 2010). "Stabilisation of the α-subunit of the hypoxia-inducible transcription factor 1 (HIF-1α) is a critical step in the adaptation of tumour cells to hypoxia." (PMID 20461082, 2010). "Nevertheless, there are also reports that HIF-1α null tumors grow unexpectedly fast, and that tumor cells with HIF-1α(-/-) tumors are more proliferative and less apoptotic than those with HIF-1α(+/+) even when tumor vessel formation was impaired." (PMID 20932347, 2010). "CA IX and XII seem to be regulated by similar mechanisms, as transcription of these isozymes is induced in tumours under hypoxic conditions through hypoxia inducible factor-1 alpha (HIF-1α)-mediated pathways." (PMID 20398423, 2010). "Inhibition of HIF-1α, a critical master gene that regulates tumor angiogenesis, growth, survival, and resistance, has been shown recently to be through downregulation of reactive oxygen species and stabilization of prolylhydoxylase 2 and 3 by MSC." (PMID 20445750, 2010). "The increased expression of HIF1α inside tumour nodules, confirms the vast oxygen need of the malignant hepatocytes." (PMID 20727157, 2010). "This does not correlate with clinical reports that hypoxia and/or HIF-1α are predictive of poor outcome in these tumours." (PMID 20637078, 2010). "As expected, eradication of HIF-1α -active cells, the most invading and metastatic cells, impairs tumor progression and dissemination." (PMID 24281221, 2010). "Conversely, in normal SVZ cells BMP2 was operating in an opposite way, promoting a nearly 10% increase of HIF-1α activity, pointing to differences between normal and tumor cells in BMP2 responsiveness." (PMID 19587783, 2009). "Inhibition of either HIF-1α or TGF-β signaling in the tumor cells by shRNA knockdown or expression of a dominant-negative TβRII decreased osteolytic lesion area and increased survival of mice with bone metastases compared to those bearing control cells." (PMID 19727403, 2009). "It is credible that CXCR7 can be one of the multiple genes targeted by HIF-1α suggesting that hypoxia can trigger chemokines expression and enhance malignancy of tumour cells in hypoxic area." (PMID 19352387, 2009). "A growing body of evidence indicates that HIF-1α contributes to tumor progression and metastasis both in human tumors and xenograph models." (PMID 19956670, 2009). "HIF1A, up-regulated in both tumor types, is a central player in the adaptation to hypoxia and known to be frequently activated in different tumors." (PMID 19327144, 2009).
tumor (continued). "HIF-1α (hypoxia-inducible factor-1 alpha) is involved in tumor growth as a vector to which cells adapt in hypoxia, and is also involved in cancer metastasis by increasing the expression of other angiogenesis related genes (VEGF)." (PMID 19671184, 2009). "Because HIF-1α and VEGF are intimately associated with tumor vascularization, we examined the effect of erlotinib on tumor vessels." (PMID 19657384, 2009). "This allows for the recognition of HIF-1α by the tumour suppressor von Hippel-Lindau protein, which targets HIF-1α for degradation." (PMID 19724277, 2009). "HIF-1α was predominantly identified into the cytoplasm of cancer cells in 48 out of 71 (67.6%) tumours; and 11 out of 71 (15.5%) displayed nuclear staining." (PMID 19352387, 2009). "In the present study, we measured mRNA expression of HIF-1α in tumor tissue from 110 randomly selected HCC patients." (PMID 19948069, 2009). "On univariate analysis, tumor HIF-1α protein expression level was significant for both OS (P = 0.027) and DFS (P = 0.012), which were further authenticated on multivariate analysis (P = 0.021 for OS; P = 0.007 for DFS)." (PMID 19948069, 2009). "After a single intraperitoneal injection of CoCl2 (60 mg/kg), a time-dependent increase in tumor bioluminescence was observed in U87/HIF-1α/FLuc xenografts." (PMID 19347037, 2009). "In conditions of high oxygen, HIF-1α is hydroxylated and targeted for proteasomal degradation by the von Hippel Lindau tumor suppressor." (PMID 19727403, 2009). "VEGF is released by TAMs in the tumor core in response to hypoxia and stabilization of HIF1α and HIF2α." (PMID 19696929, 2009). "On the other hand, the increase of miR-20b level of hypoxic tumor cells by transfecting miR-20b effectively decreased HIF-1α protein level." (PMID 19893619, 2009). "Such regulation model confers tumor cells to sense precisely the alteration of oxygen by the dynamic equilibrium between miR-20b and HIF-1α." (PMID 19893619, 2009). "The adaptation of HCC cells to tissue hypoxia is of central importance for tumor progression, where inducing the ubiquitous transcription factor of hypoxia-inducible factor-1α (HIF-1α) expression appears to be a critical step." (PMID 19948069, 2009). "Erlotinib treatment of human tumor cells in vitro and mice bearing xenografts in vivo led to decreased HIF-1α and VEGF expression." (PMID 19657384, 2009). "Recent studies have shown overexpression of HIF-1α in many human cancers with an advanced tumor grade, implying HIF-1α as an independent prognostic factor of cancer." (PMID 20035632, 2009). "In this regard, it is interesting that in early stages of carcinogenesis, even before histological evidence of angiogenesis or invasion, the tumor cells in different tissues exhibit overexpression of HIF-1α." (PMID 19564950, 2009). "Fifty percent of basal-like tumours expressed HIF-1α, and more than half expressed at least one of the PHD enzymes and FIH-1." (PMID 19165203, 2009). "HIPK2 is also a transcriptional co-repressor of hypoxia-inducible factor-1α (HIF-1α) restraining tumor angiogenesis and chemoresistance." (PMID 19714248, 2009). "As expected, the result showed that the central tumor tissues were positively stained with anti-HIF-1α antibody; however, the marginal tumor tissues were stained negatively." (PMID 19893619, 2009). "There was also a wide range of HIF1A mRNA expression in the tumours (0.16–12.1; fold range 76; mean 1.70) compared with ‘normal’ epithelium." (PMID 19568272, 2009). "This is unlikely to be due to spatial reasons because TMA are ideal for investigating relationships between biomarkers as the same area of tumour is being examined, but is probably due to the difference in half-lives of HIF-1α and CAIX." (PMID 19165203, 2009). "Focal adhesion kinase (FAK) is also important in promoting VEGF-induced tumor angiogenesis whereas the expression of HIF-1α depends on FAK and PI-3 kinase activation in cancer cells." (PMID 19919679, 2009).
tumor (continued). "Evidence that this approach is a useful one can be found in the fact that experimental and clinical studies have shown that agents that target the HIF1A/VEGF network can decrease tumor growth and prolong survival in both animals and humans." (PMID 19732454, 2009). "Meanwhile, by a comparable approach, we silenced HIF-1α expression in hypoxic tumor cells using HIF-1α siRNA." (PMID 19893619, 2009). "Staining for HIF-1α in bone metastases tumor sections was decreased in shHIF bone metastases compared to parental and shNT controls, confirming the stability of HIF-1α knockdown throughout the in vivo experiment." (PMID 19727403, 2009). "Genetic inhibition of either HIF-1α or TGF-β in tumor cells provides proof of principle that these signaling pathways promote bone metastasis through tumor-autonomous effects." (PMID 19727403, 2009). "HIF-1α and VEGF status were significantly associated with tumor stage, lymph nodes and liver metastases (P < 0.05)." (PMID 20003271, 2009). "Hypoxia-mediated HIF-1α stabilization and NF-κB activation play a key role in carcinogenesis by fostering cancer cell survival, angiogenesis and tumor invasion." (PMID 19956670, 2009). "Subsequently, the sensitivity and specificity of immunofluorescence assays for the detection of VEGF, VEGFR2 and HIF-1α in CTCs were evaluated on cytospins of tumor cells spiked in PBMCs obtained from healthy volunteers." (PMID 19919679, 2009). "Although this result is in line with one previous study showing specific HIF-1α staining in 29% of T1 tumours, two other articles reported strikingly different results (HIF-1α positivity in 68 and 100% of T1 tumours)." (PMID 19223895, 2009). "Staining for HIF-1α and tumor hypoxia were decreased in bone metastases sections from 2ME2-treated animals, demonstrating on-target effects of 2ME2 in tumor cells in vivo." (PMID 19727403, 2009). "HIF-1α showed predominantly nuclear expression in tumour cells, whereas PHDs and FIH showed both nuclear and cytoplasmic staining as previously reported." (PMID 19724277, 2009). "Despite a physiologic tumour samples variability, we recorded a 40% reduction of HIF-1α transcriptional activity under hypoxia following 8 hr of BMP2 treatment compared to untreated cells." (PMID 19587783, 2009). "More recently, intermittent hypoxia has been shown to induce elevated levels of HIF-1α transcription and tumor invasiness over continuous hypoxia." (PMID 19727397, 2009). "HIF1A immunohistochemistry and HIF1A mRNA expression for the 32 individual tumours examined were positively correlated, although the significance was borderline (Spearman's rho 0.325, P=0.07)." (PMID 19568272, 2009). "Carbonic anhydrase IX is not present in normal breast tissues, but is upregulated in invasive tumours with increasing intensity, with increasing distance from tumour vessels tightly under the regulation of HIF-1α." (PMID 19165203, 2009). "We noted robust nuclear expression of HIF-1α at the invading tumour edge, confirming previously published results." (PMID 19223895, 2009). "Under hypoxia, a condition often found in solid tumors, HIF-1α is activated to induce target genes involved in chemoresistance, inhibition of apoptosis and tumor progression." (PMID 19128456, 2009). "They decrease tumor cell expression of hypoxia-inducible factor 1-α (HIF-1α) and vascular endothelial growth factor (VEGF)." (PMID 19657384, 2009). "In fact, hypoxia and activation of the HIF-1α pathway are characteristic of many types of tumors and can be indicative of tumor aggressiveness." (PMID 19727397, 2009). "The inverse correlation between MITF and HIF1a was also observed upon application of our signature to independent tumour data suggesting it is a biologically relevant in vivo." (PMID 20041153, 2009). "The data indicate that 2ME2 effectively inhibits HIF-1α expression within the tumor microenvironment." (PMID 19727403, 2009).